KDM6A (lysine demethylase 6A)
Diseases named in the same sentence as KDM6A in open-access papers (continued):
Sharing a sentence is not in itself a finding about the gene and the disease.
bladder cancer (77 papers, 2014 to 2026). "KDM6A (Lysine Demethylase 6A), an enzyme responsible for the demethylation of H3K27me2/3, exhibits a high mutation frequency in bladder cancer." (PMID 40600050, 2025). "KDM6A often functions as a tumor suppressor, particularly in bladder cancer, where mutations can lead to loss of function." (PMID 40860181, 2025). "KDM6A knockout in mice significantly increased bladder cancer risk in females, while males remained unaffected due to compensation by the Y-chromosomal homolog Uty (homologous gene of KDM6A with redundant function)." (PMID 41019050, 2025). "The mutation rate of KDM6A was higher in female patients than in male patients in several cohorts in bladder cancer and upper tract urothelial carcinoma." (PMID 39941725, 2025). "Loss of function of KDM6A, a frequently mutated epigenetic regulator in bladder cancer, triggers downstream epigenetic alterations that promote tumour progression." (PMID 40806634, 2025). "In this context, targeting the gain-of-function effects of such mutations represents a promising therapeutic avenue for KDM6A-mutant bladder cancers." (PMID 40806634, 2025). "For example, the histone methyltransferase gene KMT2D (also known as MLL2) and the histone demethylase gene KDM6A (UTX) are mutated in approximately 20%–30% of bladder cancers, as reported by The Cancer Genome Atlas (TCGA) analyses." (PMID 40918525, 2025). "In the bladder cancer with higher frequency of KDM6A inactivation mutation, increased KI67 labeling index, upregulated glycolysis, DNA repair, mTORC1 signaling, features of the unfolded protein response, and altered cholesterol homeostasis were observed." (PMID 38840262, 2024). "In a previous study, KDM6A expression and its downstream effects were found to be lost in bladder cancer as a result of inactivating mutations." (PMID 39118085, 2024). "The loss of KDM6A leads to decreased expression of p21 and Perp, increasing susceptibility to bladder cancer." (PMID 39731171, 2024). "Kaneko and Li were able to perform a novel study using sex-reversed mice to identify hormonal influences from epigenetic factors in bladder cancer to ultimately conclude that KDM6A loss independently contributes to the male sex bias in bladder cancer." (PMID 38398136, 2024). "KDM6A-deficient bladder cancer cell lines show a loss of interaction with FOXA1, normally involved in urothelial differentiation, and a redistribution of transcription factor ATF3, further repressing FOXA1-target genes and activating cell cycle progression." (PMID 38540132, 2024). "Transcription factor motif analysis revealed HES1 to be enriched at KDM6A peaks identified in the T24 bladder cancer cell line; moreover, it has a truncating mutation in KDM6A and lacks a demethylase domain." (PMID 36980177, 2023). "Mutations identified in KDM6A in bladder cancer have loss-of-function characteristic, and there are many mutations identified within the intrinsically disordered region (IDR) of KDM6A, with one major mutation hotspot at position Q555." (PMID 36980177, 2023). "Cohort analysis has shown an association between reduced KDM6A expression and female bladder cancer progression." (PMID 38283839, 2023). "One of the most highly mutated genes in bladder cancer is KDM6A, which functions as an H3K27 demethylase and is one of the MLL3/4 complexes." (PMID 36980177, 2023). "Lysine-specific demethylase 6A is one of the most commonly mutated genes in bladder cancer (KDM6A), a tumor suppressor found on the X chromosome (Xp11.3)." (PMID 38283839, 2023). "KDM6A has been found to be more highly mutated in female-sex bladder cancer patients than in male bladder cancer patients." (PMID 37666817, 2023). "KDM6A mutation in bladder cancer is associated with immune escape of tumor cells and reduces infiltration of immune cells." (PMID 36684065, 2023).
bladder cancer (continued). "KDM6A is highly expressed in women when compared to men, yet the mutation frequency of KDM6A is higher in female-gendered bladder cancer patients." (PMID 37666817, 2023). "In bladder cancer, KDM6A mutations lead to lower numbers of tumor-infiltrating immune cells, increases in inflammatory signaling, and promotion of tumor immune escape, which facilitates tumor progression." (PMID 37666817, 2023). "We found that KDM6A, an X chromosome‐linked histone lysine demethylase, was frequently mutated in bladder cancer not only in European and American populations, but also in Asian patients." (PMID 36052737, 2022). "To provide further experimental corroboration of their overlapping role in the context of bladder cancer, we used the TCGA bladder cancer cohort to examine the effects of mutations in KDM6A and KMT2D on a number of putative downstream targets of the complex." (PMID 35073341, 2022). "Another study showed that KDM6A was highly mutated in multiple cancer types, particularly bladder cancer, by sequencing genes from 4742 tumor samples from 21 cancer types." (PMID 36052737, 2022). "Bladder cancer with KDM6A mutation increased susceptibility of EZH2 inhibitor through activation of natural killer cell signaling." (PMID 35784457, 2022). "Pernicious mutations in KDM6A are present in many cancer types, including urothelial carcinoma, bladder cancer, renal papillary cell carcinoma, some B/T‐cell lymphomas, and squamous cell carcinomas in the lung, head, and neck." (PMID 36052737, 2022). "KDM6A has been reported to be inactivated by mutations in 70% of non-invasive bladder cancer causing a loss of KDM6A expression." (PMID 34220955, 2021). "KDM6A is also mutated in numerous solid tumors such as bladder cancer, prostate cancer, and breast cancer, and depletion of KDM6A led to increased expression of EMT transcription factors, Snail, ZEB1, and ZEB2." (PMID 33808542, 2021). "In multiple myeloma and bladder cancer, KDM6A loss confers sensitivity to inhibitors of the EZH2 methyltransferase, while KDM6A loss in pancreatic cancers sensitizes to bromodomain and extra-terminal (BET) and histone deacetylase (HDAC) inhibitors." (PMID 34950587, 2021). "Bladder cancer has one of the highest frequencies of KDM6A mutations, which are typically truncating mutations compromising the catalytic JmjC domain." (PMID 33003334, 2020). "KDM6A loss accelerates tumor initiation and progression of various in vitro and in vivo models for leukemia, lymphoma, pancreatic, and bladder cancer." (PMID 33330090, 2020). "In conclusion, our results suggest that bladder cancer cells and xenografts with KDM6A and SWI/SNF family member mutations can benefit from EZH2 inhibition that increases NK cell activity leading to reduction in cells with pluripotency potential." (PMID 30692641, 2019). "In our studies, EZH2 inhibition in HT1376 and T24 bladder cancer cells with KDM6A and/or SWI/SNF family member mutations increased levels of transcripts associated with NK cell activity." (PMID 30692641, 2019). "Similar to rhabdoid and ovarian tumors with SWI/SNF mutations, complete loss of KDM6A protein sensitizes bladder cancer cell lines and patient-derived xenografts to EZH2 inhibition." (PMID 30692641, 2019).
bladder cancer (continued). "Although these mutations occur at low frequency in most cancers, KDM6A mutations in bladder carcinoma are quite common (20%–29%)." (PMID 24622842, 2014). "KDM6A mutations are more common in bladder cancer and breast cancer, with some evidence suggesting that KDM6A loss may promote tumor progression through the TGF-β pathway." (PMID 40297816, 2025). "In summary, bladder cancer’s alterations in histone modification pathways–whether via mutation (KDM6A, ARID1A, KMT2D) or overexpression (EZH2, HDACs) – are a central component of its biology and interact with aging." (PMID 40918525, 2025). "Furthermore, loss-of-function mutations in KDM6A render bladder cancer cells susceptible to EZH2 inhibitors, which drive cell differentiation and death." (PMID 39938867, 2025). "KDM6A loss triggers an epigenetic switch that disrupts urothelial differentiation and induces a neoplastic state characterized by increased cell proliferation in bladder cancer." (PMID 38840262, 2024). "Previous studies have shown that mutations in KDM6A lead to highly active glycolysis in bladder cancer, but the molecular mechanism remains unclear." (PMID 38840262, 2024). "Importantly, we believe that the KDM6A-TLE1-HES1 regulatory axis we defined makes a valuable contribution to the understanding of epigenetic deregulation in bladder cancer with regard to the mutations observed in KDM6A." (PMID 36980177, 2023). "KDM6A is one of the most frequently mutated genes in bladder cancer." (PMID 36980177, 2023). "There is a close association between KDM6A and bladder cancer invasion." (PMID 36684065, 2023). "KDM6A is mutated in various cancers such as breast cancer and other forms of bladder cancer." (PMID 35073341, 2022). "Compelling biological evidence supports that tazemetostat may be effective in bladder cancer patients with KDM6A mutation." (PMID 36052737, 2022). "Moreover, chromatin remodeling genes, such as ARID1A and KDM6A were frequently mutated in bladder cancer." (PMID 33407469, 2021). "KDM6A, a histone demethylase, is frequently mutated in bladder cancer (BCa)." (PMID 34006303, 2021). "Somatic mutations in KDM6A have been found in a broad range of human cancers, including multiple myeloma, renal cell carcinoma, bladder cancer, head and neck squamous cell carcinoma, acute lymphoid leukaemia, prostate cancer, medulloblastoma, and pancreatic adenocarcinoma." (PMID 34006303, 2021). "Furthermore, in bladder cancer KDM6A loss activates cytokine and chemokine pathways, and these cells are more sensitive to combined inhibition of IL-6 and CCL2." (PMID 34950587, 2021). "Furthermore, female patients with non-invasive bladder cancer are approximately two-fold more likely than men (74% vs. 42%) to harbor KDM6A mutations." (PMID 32197306, 2020). "In cancer, except for bladder cancer, the frequency of mutation in the KDM6A gene is rather low." (PMID 31201358, 2020). "This EZH2 sensitivity in bladder cancer is based on total loss of KDM6A protein." (PMID 30692641, 2019). "Furthermore, KDM6A mutations in bladder carcinoma associate with earlier grade and are inversely correlated with stage." (PMID 24622842, 2014). "Furthermore, genetic studies suggest the mosaic loss of Y chromosome in blood in men may be associated with increased bladder cancer risk in men and some X chromosome-linked genes (KDM6A) may confer protection in women." (PMID 40341249, 2025). "However, KDM6A appears to function as a tumor suppressor, and recent results implicate KDM6A loss in bladder cancer progression and resistance to the CD38 blocker daratumumab in multiple myeloma, potentially contraindicating the general use of KDM6A/B inhibitors." (PMID 39403928, 2024).
bladder cancer (continued). "Thus, KDM6A has tumor suppressor function, and, as an X-linked gene, it may be an important factor of the male bladder cancer sex bias, which potentially acts in concert with AR/hormonal factors." (PMID 38398136, 2024). "Therefore, we investigated whether EZH2 inhibition differentially affects bladder cancer cell lines with mutations in either KDM6A alone or both KDM6A and SWI/SNF family members." (PMID 30692641, 2019). "Transcriptomic analyses indicate that KDM6A-mutant bladder cancers have downregulation of multiple interferon and chemokine signaling pathways required for effective tumor immunity." (PMID 40918525, 2025). "Previous studies have shown that KDM6A contributes to sex disparities in bladder cancer (BCa) with 3–5 times more protective effects in females." (PMID 41019050, 2025). "Research has demonstrated that KDM6A functions as a tumor suppressor by inhibiting the proliferation, migration, and invasion of bladder cancer cells, and its expression is strongly correlated with patient prognosis." (PMID 40600050, 2025). "CCDC8 expression levels in bladder cancer are significantly associated with the mutation frequencies of various genes, notably FGFR3 and KDM6A." (PMID 39744495, 2025). "Chromatin regulation genes, including KDM6A, KMT2D, EP300, and ARID1A, show high rates of mutation in bladder cancer, as demonstrated here and in multiple cohort studies." (PMID 41373802, 2025). "At molecular level, KDM6A promotes the expression level of ARHGDIB to downregulate Rac1 in suppressing metastasis of bladder cancer cells." (PMID 36684065, 2023). "The use of nanostructures enabled enhanced exposure of KDM6A‐mRNA to bladder cancer site and provided sustained delivery." (PMID 36684065, 2023). "As the bladder cancer cell line included in our study, T24 is not a wild type for KDM6A; thus, we additionally compared our data to published ChIP-seq data for the bladder cancer cell line KDM6A." (PMID 36980177, 2023). "Among the chromatin-modifier mutations observed in bladder cancer, a few of them are especially high, including KMT2D (28%), KDM6A (26%), and ARID1A (25%), which are observed in muscle-invasive bladder cancer." (PMID 36980177, 2023). "Collectively, our results underscore the role of KDM6A in the regulation of Notch signaling and its potential deregulation in bladder cancer." (PMID 36980177, 2023). "Collectively, our work provides important contributions to the understanding of KDM6A malfunction in bladder cancer." (PMID 36980177, 2023). "An experiment has focused on delivery of KDM6A‐mRNA by mucoadhesive nanostructures in bladder cancer therapy." (PMID 36684065, 2023). "Lysine demethylase 6A (KDM6A) in bladder cancer cells can inhibit Rac1 activation to prevent cell mobility." (PMID 37049739, 2023). "A recent study also demonstrated that the expression of wild-type KDM6A or a KDM6A-demethylase-mutant in a KDM6A-null bladder cancer cell line resulted in similar KDM6A genomic localizations." (PMID 36980177, 2023). "We recently developed mucoadhesive nanoparticles for intravesical delivery of lysine-specific demethylase 6A (KDM6A) mRNA to overcome physiological bladder barriers for treatment of bladder cancer metastasis." (PMID 39872158, 2022). "For example, the X chromosome protects against bladder cancer in female mice via a KDM6A-dependent epigenetic mechanism." (PMID 35399508, 2022).
bladder cancer (continued). "The role of KDM6A as a tumor suppressor in bladder cancer has been studied both in vitro and in vivo." (PMID 35784457, 2022). "Metformin has also been recognized as a catalytic inhibitor of KDM6A, and is currently in phase II clinical trials of bladder cancer (NCT03379909)." (PMID 34950587, 2021). "To verify the role of KDM6A in predicting clinical outcome in BCa patients, we performed IHC on a tissue microarray containing 56 human bladder cancer samples and found that low KDM6A protein expression was associated with poorer overall survival (OS)." (PMID 34006303, 2021). "The study using KDM6A-knockout bladder cancer cells and patient-derived xenograft model suggested that EZH2 (enhancer of zeste homolog 2, H3K27 methylase) inhibition is a potential therapeutic target for bladder cancer with the mutations." (PMID 32842545, 2020). "The male paralogue of KDM6A is the UTY gene located on Yq11 and is mutated in approximately 9% of male non-invasive bladder cancers." (PMID 32197306, 2020). "Here we show that EZH2 inhibition is most effective in bladder cancer cells with both SWI/SNF family member and KDM6A mutations, and is capable of augmenting cisplatin response." (PMID 30692641, 2019). "We exploit the loss of function mutations in KDM6A and SWI/SNF complex to make bladder cancer cells susceptible to EZH2-based epigenetic therapy that activates an immune response to drive tumor cell differentiation and death." (PMID 30692641, 2019). "Furthermore, the FOXA1-KDM6A-ARHGDIB axis has been identified as a critical pathway in bladder cancer metastasis, underscoring the therapeutic potential of targeting KDM6A in clinical settings." (PMID 40600050, 2025). "In addition, mucoadhesive mRNA nanoparticles used for the intravesical delivery of KDM6A-mRNA in mice bearing orthotopic Kdm6a-null bladder cancer reduced bladder size and weight, and significantly decreased lymph node volume and Ki-67 expression." (PMID 40940894, 2025). "In bladder cancer, KDM6A inhibits colony formation by downregulating FGFR3 expression." (PMID 39938867, 2025). "Similarly, alternative splicing of kdm6a mRNA controls the subcellular localization of the Kdm6a in human bladder cancer cells and normal epithelia." (PMID 40305565, 2025). "Disruption of KDM6A is one of the most common somatic alternations in bladder cancer." (PMID 38840262, 2024). "To validate that KDM6A alterations occurred at an increased frequency within RT-associated bladder cancer, we calculated the proportion of KDM6A altered tumors in the DFCI validation cohort and in a non-RT cohort, TCGA bladder study." (PMID 39113632, 2024). "They reported that loss of KDM6A consistently increased bladder cancer risk only in female knockout mice but not in male knockout mice." (PMID 38982123, 2024). "Thus, there are some intriguing associations in our current understanding of sex bias in bladder cancer: AR signaling and T-cell exhaustion, LOY (and KDM5D demethylase loss) and T-cell exhaustion, and sex-dependent demethylase (KDM6A) gene loss." (PMID 38398136, 2024).